IL17A (interleukin 17A)
Diseases named in the same sentence as IL17A in open-access papers (continued):
Sharing a sentence is not in itself a finding about the gene and the disease.
thyroid cancer (17 papers, 2012 to 2025). "We observed IL-17A expression in cytoplasm of thyroid cancer cells from all patients." (PMID 32139737, 2020).
allergic contact dermatitis (16 papers, 2011 to 2025). An inflammatory skin condition caused by an immune response to direct contact between the skin and an allergen. "Using 1-Fluoro-2,4-dinitrobenzene applied to mice as a model of allergic contact dermatitis, another study established that local disease memory is associated with the accumulation in the epidermis of CD8+ TRMs that are able to produce IL-17A and IFN-γ." (PMID 34445713, 2021).
amyotrophic lateral sclerosis (16 papers, 2014 to 2025). Amyotrophic lateral sclerosis (ALS) is a neurodegenerative disease characterized by progressive muscular paralysis reflecting degeneration of motor neurons in the primary motor cortex, corticospinal tracts, brainstem and spinal cord. "Levels of IL-17a have been found to be increased in many neurodegenerative diseases, including AD, PD, MS, and amyotrophic lateral sclerosis (ALS)." (PMID 37408205, 2023). "Among them the most statistically significant four pathways were Amyotrophic Lateral Sclerosis Signaling, G-Protein Coupled Receptor Signaling, Relaxin Signaling and IL-17A Signaling in Airway Cells." (PMID 31791392, 2019). "For example, although the use of anti-IL-17A drugs has seen efficacy in the treatment of psoriasis, it is clinically invalid in the treatment of amyotrophic lateral sclerosis (ALS), rheumatoid disease, and experimental autoimmune encephalomyelitis (EAE)." (PMID 36438975, 2022).
glaucoma (16 papers, 2019 to 2025). Increased pressure in the eyeball due to obstruction of the outflow of aqueous humor. "Mice with experimental glaucoma have shown a significant increase in IL-17A expression by microglia, induced by acute IOP elevation." (PMID 39125762, 2024). "Glaucoma is a blinding disease whose pathogenesis is not yet fully understood, so further studies are needed to understand the role of IL-17A in glaucoma." (PMID 35392087, 2022). "The frequency of IL-17A-secreting cells and IL-17A+ CD4 T cells is significantly higher in patients with glaucoma compared with controls." (PMID 33829024, 2021). "Immunofluorescent images and western blotting showed that the expression of inflammatory mediators, such as IL-17A, was increased, and microglial cells were active in our glaucoma model." (PMID 33829024, 2021). "To our knowledge, we are the first to report increased IL-17A expression in an experimental glaucoma model." (PMID 33829024, 2021). "TXNIP may also be involved in this process by regulating the microglial immune response in synergy with the impact of IL-17A in the early stage of experimental glaucoma." (PMID 39736512, 2024). "In our previous study, we found that IL-17A was dynamically involved in regulating the transformation of the microglial phenotype in experimental glaucoma, but the underlying mechanism was not fully elucidated." (PMID 39736512, 2024). "However, the exact role of IL-17 in glaucoma has yet to be fully elucidated, and further studies are needed to clarify the role of IL-17A in glaucoma." (PMID 39125762, 2024). "In recent years, some researchers have studied IL-17A levels in patients with glaucoma." (PMID 33829024, 2021). "In recent years, some researchers have studied the IL-17A levels in patients with glaucoma." (PMID 33132897, 2020). "Furthermore, suppressing IL-17A shows promise as an innovative glaucoma therapeutic target." (PMID 39125762, 2024). "IL-17A, a subfamily of IL-17, regulates the retinal immune response and RGC death in experimental glaucoma by promoting retinal microglial activation." (PMID 39125762, 2024). "Elevated levels of TNFα, IFNγ, IL17A, and TGFβ are observed in PACG, which is in alignment with previous reports on glaucoma." (PMID 39184151, 2024). "In another study, however, researchers have demonstrated that the frequency of IL-17A-secreting cells and IL-17A+ CD4 T cells is significantly higher in patients with glaucoma than in controls." (PMID 33132897, 2020). "In glaucoma patients, although IL-17A plasma levels were not significantly altered, elevated IL-17A-secreting cells were observed." (PMID 34819548, 2021). "Our understanding of these processes is still lacking, particularly in the role of IL-17A in the pathogenesis of glaucoma." (PMID 33132897, 2020). "Because these studies measured IL-17A in peripheral blood in human patients and glaucoma is a complex disease whose pathogenesis has not been fully understood, further studies are needed to understand the role of IL-17A in glaucoma." (PMID 33132897, 2020).
Hyperkeratosis (16 papers, 2014 to 2025). Hyperkeratosis is a histopathological term defining a thickened stratum corneum and may be present in many different skin conditions, with many possible overlaps. "In the present study, we also observed similar manifestations, such as increased skin redness, scaling, acanthosis, elongation of rete-like ridges, hyperkeratosis, increased levels of IL-6 and IL-17A, and acanthosis." (PMID 37686332, 2023). "IL-17A treated STAT3 mice skin lesions displayed the pathological features of hyperkeratosis and parakeratosis." (PMID 37465147, 2023).
interstitial lung disease (16 papers, 2011 to 2025). A diverse group of lung diseases that affect the lung parenchyma. "The results indicate an SSc-specific increase in the number of Th cells producing IL-22 and IL-17A, skewed to preferential homing into the lung and associated with interstitial lung disease (ILD)." (PMID 21996293, 2011). "IL-17A may promote lung fibroblast proliferation by stimulating IL-17RA, and cause corticosteroid insensitivity in interstitial lung disease via upregulating glucocorticoid receptor β (GR-β) expression or inhibiting typical corticosteroid genes." (PMID 36944820, 2023). "By univariate analysis the clinical manifestations associated to IL-17A, TGFβ, FGF2 and CTGF production by PBMCs were interstitial lung disease (ILD), PAH and DU (p<0,01)." (PMID 35693738, 2022). "Finally, SSc interstitial lung disease (ILD) was strongly associated with higher numbers of IL-22 and, to a lesser extent, IL-17A-producing cells." (PMID 21996293, 2011). "Similarly, the level of IL-17A was significantly elevated as compared to lung cancer and interstitial lung disease (ILD)." (PMID 36944820, 2023). "IL17, TGFβ, CTGF and FGF2 levels were higher in SSc patients with interstitial lung disease and digital ulcers, whereas IL-17A production was lower in patients with PAH." (PMID 35693738, 2022). "Enhanced IL-6 signaling has been shown to contribute to interstitial lung disease (ILD) pathogenesis, through the IL-6/STAT3/IL-17A signaling pathway." (PMID 36543914, 2022).
intestinal infection (16 papers, 2009 to 2025). "In this study, CEO decreased the cytokines IL-6, IL-8, and IL-17A, which were elevated by intestinal infection, and improved inflammatory status." (PMID 40509258, 2025). "Studies have shown that ILC3s promote protective immunity against gastrointestinal infection and opportunistic fungal pathogens by producing IL-17A and IL-22." (PMID 35844574, 2022). "Genetic ablation of RANKL specifically in IL3C cells leads to an increased number of these cells with enhanced levels of pro-inflammatory cytokines such as interleukin-17A (IL-17A) and IL-22 during intestinal infection." (PMID 32850393, 2020). "IL-17A was reported to participate in the induction of inflammation in chickens during intestinal infection." (PMID 29783653, 2018). "ILC3s are important innate sources of IL-17A, IL-22 and IFN-γ, which play crucial roles in regulating intestinal infection and maintaining homeostasis." (PMID 39695888, 2024). "In an intestinal infection with C. rodentium, IL-22 is produced earlier than IL-17A and it plays a decisive role, whereas IL-17A does not." (PMID 23379788, 2013). "Additionally, Rag2γc mice exhibited significantly lower levels of IL-22 but not IFN-γ or IL-17A than wild-type B6 mice, suggesting that IL-22 plays a role in C. albicans gastrointestinal infection." (PMID 33488563, 2020).
Kawasaki disease (16 papers, 2014 to 2025). A rare inflammatory disease characterized by an acute febrile, systemic, self-limiting, medium-vessel vasculitis primarily affecting children. "Different T cell subsets and IL17-A are the difference between Kawasaki disease and MIS-C, while the similarity between them is attributed to the adverse immune reaction by auto-antibodies." (PMID 41226731, 2025). "In consistent with these previous reports, we found that CD14+ monocytes from patients with Kawasaki disease only effectively promoted the activation and differentiation of naïve CD4+ T cells into IFN-γ-producing Th1 and IL-17A-producing Th17 cells under direct contact condition." (PMID 32276581, 2020). "For example, IL-17A mediates hyperinflammation in the Kawasaki disease, but not in MIS-C, so IL-17A blocking agents could be considered in patients with severe Kawasaki disease but not in MIS-C." (PMID 36361640, 2022).
osteosarcoma (16 papers, 2016 to 2026). A usually aggressive malignant bone-forming mesenchymal neoplasm, predominantly affecting adolescents and young adults. "Microarray analysis revealed that osteosarcoma samples from patients exhibited a higher IL-17RA expression relative to either IL-17A and IL-17F." (PMID 38062130, 2023). "Relevant to osteosarcoma, serum IL-17A levels are reportedly elevated in patients with metastatic osteosarcoma, and IL-17A/IL-17RA interaction reportedly promotes osteosarcoma metastasis in nude mice." (PMID 38062130, 2023). "Previous study reported that IL-17A and IL-17R interaction enhanced the metastasis of osteosarcoma cells via the expression of VEGF, MMP-9 and CXCR4." (PMID 26850593, 2016). "IL-17 can facilitate the susceptibility of osteosarcoma cells to NK cell lysis, and IL-17A/IL-17RA interaction can promote osteosarcoma cells metastasis, indicating that targeting IL-17 may be a novel promising strategy to treat osteosarcoma patients." (PMID 37732314, 2023). "Besides, IL-17A/IL-17RA interaction promoted metastasis of osteosarcoma cells." (PMID 30849987, 2019). "As in AX cells, proliferation of MG63 cells, a human osteosarcoma line, was not stimulated by IL-17A." (PMID 38062130, 2023).
Pruritus (16 papers, 2016 to 2025). Pruritus is an itch or a sensation that makes a person want to scratch. "Patients treated with anti-IL-17A/F BAs were also prone to pruritus, with an incidence of 9.09%." (PMID 36817423, 2023).
sarcopenia (16 papers, 2022 to 2026). Progressive decline in muscle mass due to aging which results in decreased functional capacity of muscles. "Positive associations were present between the severity of sarcopenia and IL-6 and IL-17A levels, whereas there was an inverse correlation between the presence of sarcopenia and the IL-10 level." (PMID 35237317, 2022). "To investigate this, we measured serum concentrations of the inflammatory cytokines IL-6, TNF-α, and IL-17A and estimated the association between IL-6 and IL-17A levels in elderly individuals with sarcopenia." (PMID 35237317, 2022). "Since sarcopenia is associated with elevated levels of IL-6, IL-17A, and TNF-α, patients with sarcopenic obesity may face a higher risk of swelling due to this combined inflammatory burden." (PMID 41233862, 2025). "A positive association was found between the high level of IL-6, IL-17A, and TNF-α and the prevalence of sarcopenia for both men and women." (PMID 35237317, 2022). "Increased levels of IL-1α, IL17A and CXCL5 have been linked to sarcopenia and cardiotoxicity." (PMID 36611902, 2022). "Our study has demonstrated that IL-6 and IL-17A were elevated in patients with sarcopenia." (PMID 35237317, 2022). "In this study, higher EM DN (CD4- CD8-) %DN was proven to be causally associated with higher levels of IL-17A, higher scores of AALM, lower levels of SIRT2, LIF-R, and DNER, and lower risk of poor hand grip strength (EWGSOP), which might be protective causal factors of sarcopenia." (PMID 39229276, 2024). "Positive associations were present between the severity of sarcopenia and IL-6, IL-17A, and TNF-α levels, while there was an inverse correlation between the presence of sarcopenia and IL-10 level." (PMID 35237317, 2022). "We found that the levels of inflammatory cytokines IL-6, IL-17A, and TNF-α were increased in sarcopenia patients, while the IL-10 level declined." (PMID 35237317, 2022). "Our study performed a cross-sectional analysis of serum concentrations of IL-6, IL-10, IL-17A, and TNF-α in the context of sarcopenia in elderly individuals." (PMID 35237317, 2022). "Higher IL-6, IL-17A, and TNF-α levels were observed in participants with sarcopenia (P < 0.05)." (PMID 35237317, 2022).
tendinopathy (16 papers, 2016 to 2025). "By using the ex vivo rat tendon fascicle model and the in vivo rat rotator cuff tendinopathy model, we aimed to further elucidate the biological mechanisms of IL-17A blockade underlying the reported therapeutic effects in human early-stage tendinopathy." (PMID 39988349, 2025). "In our in vivo rat disease model of rotator cuff tendinopathy, we were attentive but not successful in exploring potential antinociceptive effects of IL-17A blockade on tendinopathic pain, another hallmark of tendinopathy." (PMID 39988349, 2025). "Interleukin (IL)-17A, a pro-inflammatory cytokine that is linked to the pathology of several inflammatory diseases, has been shown to be upregulated in early human tendinopathy and to mediate inflammatory and tissue remodelling events." (PMID 35004653, 2021). "We show that IL-17A stimulates signalling cascades that promote tendon inflammation and tendon matrix degeneration, proposed to be causally linked with the clinical manifestation of pain and impaired tendon function in tendinopathy." (PMID 39988349, 2025). "Strategies to interfere with IL-17A signaling and the ability of ERK/Atk inhibitors to reduce IL-17A associated effector function therefore may provide novel therapeutics in human tendinopathy." (PMID 27263531, 2016). "In the present work, we induced IL-17A pathway activation in cells derived from healthy tendons as a mechanistic experimental model to mimic the suggested IL-17A-mediated pathogenesis of tendinopathy." (PMID 39988349, 2025). "The concomitantly observed improvement in tendon and shoulder function indicates that the biological mechanism of action of IL-17A blockade has the potential to interfere with the pathobiology of tendinopathy." (PMID 39988349, 2025). "The present preclinical study elucidates the biological mechanisms of IL-17A pathway stimulation and blockade in tendinopathy." (PMID 39988349, 2025). "In the present study using RT qPCR, we demonstrate the mRNA expression of IL-17A (IL17A) in human early-stage tendinopathy, confirming our previous data." (PMID 39988349, 2025). "We provide evidence of differential expression of IL-17A mRNA (IL17A) versus other IL-17 family members in human rotator cuff early-stage tendinopathy." (PMID 39988349, 2025). "We sought evidence of interleukin 17A (IL-17A) expression in early human tendinopathy and thereafter, explored mechanisms whereby IL-17A mediated inflammation and tissue remodeling in human tenocytes." (PMID 27263531, 2016). "We propose IL-17A as an inflammatory mediator within the early tendinopathy processes thus providing novel therapeutic approaches in the management of tendon disorders." (PMID 27263531, 2016). "To characterise these IL-17A+ cells in human tendinopathy, we performed colocalisation studies and calculated the proportion of IL-17A+ cells contained in each cellular subset." (PMID 27263531, 2016). "Together these findings suggest that upregulation of the receptor ligand IL-17A is the key driver to boost signal induction in tendinopathy and that IL-17A is the main IL-17 cytokine family member contributing to the pathogenesis of human early-stage tendinopathy." (PMID 39988349, 2025). "In rotator cuff tendon biopsies of early-stage human tendinopathy, we have previously shown an increased expression of IL-17A mRNA (IL17A) and the presence of IL-17A protein in mast cells, macrophages and T cells, pointing towards a pathogenetic role of IL-17A in tendinopathy." (PMID 39988349, 2025). "Our data provide evidence that IL-17A is a key contributor to the pathogenesis of tendinopathy by promoting tendon inflammation and degeneration and that IL-17A blockade may represent a potential therapy in early-stage tendinopathy." (PMID 39988349, 2025). "The effect of IL-17A blockade was assessed on the post-transcriptional effectors because of their downstream integrated mediation of inflammation and degeneration in the pathogenesis of tendinopathy." (PMID 39988349, 2025).